LARP1B (La ribonucleoprotein 1B)
Synonyms: LARP2; FLJ10378; DKFZp434K245; DKFZp686E0316
Tractability: PROTAC: ubiquitination databases record sites on it.
Gene: Protein-coding gene on chromosome 4 (128,060,801 to 128,222,931, forward strand). Ensembl gene ENSG00000138709.
Subcellular location (Human Protein Atlas): Cytosol
Gene Ontology:
Molecular function: protein binding; RNA binding; RNA cap binding
Biological process: positive regulation of translation; mRNA stabilization
Cellular component: nucleus; cytoplasmic stress granule; cytosol
Genetic constraint (gnomAD): Loss-of-function variants: 53 observed, 71.24 expected, observed/expected ratio (o/e) 0.74, 90% interval 0.6 to 0.94. The upper end of that interval is the gene's LOEUF score, 0.94, which puts it in group 3 of 6, group 1 being the genes least tolerant of losing a copy. Missense variants: 741 observed, 817.48 expected, observed/expected ratio (o/e) 0.91, 90% interval 0.85 to 0.96. Synonymous variants: 251 observed, 270.63 expected, observed/expected ratio (o/e) 0.93, 90% interval 0.84 to 1.03.
Homologues: Orthologues: chimpanzee LARP1B (99% identical), macaque LARP1B (98% identical), dog LARP1B (91% identical), pig LARP1B (88% identical), rabbit LARP1B (88% identical), tropical clawed frog larp1b (58% identical), zebrafish larp1b (55% identical), Drosophila melanogaster larp (39% identical), rat Larp1b (33% identical), mouse Larp1b (32% identical), Caenorhabditis elegans larp-1 (31% identical), rat Larp1bl (23% identical), and 2 more. Paralogues in human: LARP1 (59% identical), LARP4 (13% identical), LARP4B (13% identical), LARP6 (8% identical), LARP7 (8% identical), SSB (7% identical).
Diseases named in the same sentence as LARP1B in open-access papers:
LARP1B is named in the same sentence as 11 diseases in open-access papers, as found by Europe PMC text mining. Sharing a sentence is not in itself a finding about the gene and the disease. The quoted sentences say what the papers report.
diabetes (1 paper, 2021). "Interestingly, diabetes increases LARP1 and LARP1B in human β-cells." (PMID 33483593, 2021). "However, the upregulation of LARP1B in diabetes might attenuate the absence of LARP1 in the responses to HFD or BCAA diet." (PMID 33483593, 2021).
mastitis (1 paper, 2022). Inflammation of breast tissue during lactation or postpartum due to an obstructed duct or infection. "Of the 12 co-expressed down-regulated genes, TFRC and MAPK6 are thought to be associated with immunity and mastitis, LARP1B and ODC1 are associated with reproductive traits, such as oestrogen and sperm quality." (PMID 35480317, 2022).
LARP1B also shares sentences with these, for which no sentence is quoted: Allergy (1 paper); asthma (1); autoimmune disease (1); autoimmune disorders (1); breast carcinoma (1); cancer (1); meningioma (1); Obesity (1); type 2 diabetes (1).